Y_RNA (Y RNA )
Gene: Miscellaneous RNA gene on chromosome 1 (153,785,720 to 153,785,821, reverse strand). Ensembl gene ENSG00000207039.
Homologues: Orthologues: chimpanzee Y_RNA (99% identical), macaque Y_RNA (97% identical). Paralogues in human: RNY3 (94% identical), Y_RNA (94% identical), RNY3P1 (93% identical), Y_RNA (93% identical), Y_RNA (92% identical), Y_RNA (91% identical), Y_RNA (90% identical), RNY3P14 (89% identical), Y_RNA (89% identical), RNY3P11 (88% identical), RNY3P16 (88% identical), Y_RNA (88% identical), and 96 more.